MET (MET proto-oncogene, receptor tyrosine kinase)
Diseases named in the same sentence as MET in open-access papers (continued):
Sharing a sentence is not in itself a finding about the gene and the disease.
schizophrenia (9 papers, 2016 to 2024). A major psychotic disorder characterized by abnormalities in the perception or expression of reality. "Their analysis revealed that the bagging ensemble algorithm with feature selection outperformed other predictive algorithms in forecasting the quality-of-life functional outcome of schizophrenia using the G72 rs2391191 and MET rs2237717 SNPs." (PMID 39546776, 2024). "A genetic implication of HGF and MET in the development of brain emerges from the literature, and various alterations in the HGF-MET pathway correlate with features of some NDDs such as ASD, schizophrenia, and non-syndromic hearing loss." (PMID 34179015, 2021). "The analysis reported that the bagging ensemble algorithm with feature selection outperformed other predictive algorithms to forecast the QLS functional outcome of schizophrenia by using the G72 rs2391191 and MET rs2237717 SNPs." (PMID 33986383, 2021). "A strong evidence of HGF-MET axis importance in the human development of nervous system comes from some studies that reveal a genetic implication of HGF and MET genes in some NDDs such as autism spectrum disorder (ASD), schizophrenia, and non-syndromic hearing loss." (PMID 34179015, 2021).
clear cell sarcoma (8 papers, 2012 to 2025). A rare malignant neoplasm with melanocytic differentiation characterized by the presence of polygonal or spindle shaped clear cells. "Finally, another fusion transcript, EWSR1/CREB1, has been implicated in upregulation of MET oncogene in clear-cell sarcoma." (PMID 23329308, 2013). "On the other hand, crizotinib, an ALK inhibitor which has been investigated to rhabodmyosarcoma with ALK expression above, is known as inhibiting other targets such as MET, and showed some clinical responses to clear cell sarcomas overexpressing MET." (PMID 31963219, 2020). "Based on previous reports clear cell sarcomas do show MET expression to a substantial extent, thus, indicating that this tumor entity should be evaluated further for MET protein expression and MET copy number changes." (PMID 25844809, 2015). "The use of MET inhibitor ARQ197 already represents a good therapeutic strategy in clear-cell sarcoma." (PMID 23329308, 2013). "A recent report finds that the MET inhibitor ARQ197 yielded a response in a phase II study of clear cell sarcoma." (PMID 23226201, 2012). "Overexpression of hepatocyte growth factor receptor (MET) is observed in clear cell sarcoma (CCS)." (PMID 40909947, 2025). "Clear cell sarcoma (CCSA) is a rare subtype of soft tissue sarcoma characterized by EWSR1 rearrangement and subsequent MET upregulation." (PMID 34885165, 2021). "Clear cell sarcoma (CCSA) is characterized by a chromosomal translocation leading to EWSR1 rearrangement, resulting in aberrant transcription of multiple genes, including MET." (PMID 34885165, 2021). "Unfortunately we could not correlate our findings of HGF expression in clear cell sarcomas with MET immunohistochemistry due to limited tissue resources." (PMID 25844809, 2015).
pulmonary fibrosis (8 papers, 2016 to 2025). Chronic progressive interstitial lung disorder characterized by the replacement of the lung tissue by connective tissue, leading to progressive dyspnea, respiratory failure, or right heart failure. "Recently it was reported that ASS1 deficiency happened in pulmonary fibrosis, MET can be activated by knocking down ASS1, then interacting with the upstream of the Src-STAT3 signaling to up-regulate the proliferation of fibroblast cells." (PMID 36147332, 2022). "Previously, we showed that cleavage of MET and generation of endogenous M10 occurs in the lungs of patients with scleroderma associated pulmonary fibrosis." (PMID 29176766, 2017). "Overall, suggesting that c-MET signaling in immune cells deregulates inflammatory recruitment and activation, ultimately leading to pulmonary fibrosis." (PMID 38909206, 2024). "To determine the influence of c-MET in immune cells in the progression of pulmonary fibrosis, we used a conditional deletion of c-Met in immune cells." (PMID 38909206, 2024). "Our results demonstrate that c-MET signaling pathway modulates uncontrolled recruitment of immune cells and activation toward a proinflammatory and profibrotic phenotype, exacerbating lung injury and ultimately culminating in lung fibrosis." (PMID 38909206, 2024). "Among the candidates, we focused on c-MET, whose role in lung fibrosis has been documented." (PMID 35392967, 2022). "We conclude that the D1398G variant of MET is associated with compromised phosphorylation and impaired HGF signaling in lung fibroblasts and AEC, two cell types implicated in the pathogenesis of pulmonary fibrosis associated with scleroderma." (PMID 27584154, 2016). "Thus, highlighting that c-MET signaling pathway may be a promising target for therapeutic strategies aimed at the treatment of lung fibrosis." (PMID 38909206, 2024). "Our findings indicated that exosomal miR-466f-3p derived from mMSCs may possess anti-fibrotic properties and prevent radiation-induced EMT through inhibition of AKT/GSK3β via c-MET, providing a promising therapeutic modality for radiation-induced lung fibrosis." (PMID 35392967, 2022). "In fact, this is corroborated by a recent study that confirms an upregulation of c-MET in the fibrotic foci either in IPF and fibrotic hypersensitivity pneumonia, reinforcing its importance in the pathogenesis of pulmonary fibrosis." (PMID 38909206, 2024). "MET is also expressed by myofibroblasts, where HGF exerts an anti-fibrotic effect and preserves organ function in bleomycin-induced lung fibrosis models." (PMID 27584154, 2016).
skin cancer (8 papers, 2013 to 2023). "In the 4th edition of the 2018 WHO classification of skin tumors, lesions in the spitzoid pathway (pathway 4) are characterized by mutations in HRAS, tyrosine kinase fusions (ALK, ROS1, RET, NTRK1/3, and MET), or serine-threonine kinase fusions (BRAF, MAP3K8)." (PMID 33040161, 2021). "In summary, we have identified the HGF/MET pathway as critical to skin tumor growth and malignant conversion in Tpl2−/− mice." (PMID 30631034, 2019).
synovial sarcoma (8 papers, 2014 to 2025). "Since PI3K was shown to be regulated by both ALK and MET signals in some tumor cells, selective induction of apoptosis in synovial sarcoma cells was mediated by abrogating these aberrant tyrosine kinase signals." (PMID 30416685, 2018). "It was reported that the synovial sarcoma Aska-SS cell line expressed an activated ALK variant and showed sensitivity to ALK inhibitors, while another synovial sarcoma cell line Yamato-SS overexpressed MET protein and exhibited sensitivity to the ALK/MET dual inhibitor, crizotinib." (PMID 30416685, 2018). "Using phosphoproteomic profiling, MET and ALK have been identified as novel targets of synovial sarcoma and are highly expressed in 58% and 14% of ES patients, respectively." (PMID 32754598, 2020). "Focusing on the synovial sarcoma subtype, they found several new RTK dependencies including ALK, PDGFRα and MET which were functionally tested in preclinical in vivo experiments and whose expression was shown to be elevated in a subset of synovial sarcoma patient specimens." (PMID 35171456, 2022). "MET and ALK expression are involved in the pathogenesis of ES and synovial sarcoma." (PMID 32754598, 2020). "While c-MET was expressed but not phosphorylated in SYO-1, a human synovial sarcoma cell line, or HDF cells, higher expression and phosphorylation of c-MET were observed in Asra-EPS and VAESBJ cells." (PMID 25098767, 2014).
thyroid tumor (8 papers, 2013 to 2025). A benign or malignant neoplasm affecting the thyroid gland. "Activation of MET mutations, at both the germline and somatic levels, and gene amplification have been reported in several cancers, including thyroid neoplasms (in which the main mutation is MET T1010I in exon 14)." (PMID 37835559, 2023).
anaplastic large cell lymphoma (7 papers, 2013 to 2022). Anaplastic large cell lymphoma (ALCL) is a rare and aggressive peripheral T-cell non-Hodgkin lymphoma, belonging to the group of CD30-positive lymphoproliferative disorders, which affects lymph nodes and extranodal sites. "In anaplastic large cell lymphoma (ALCL), a type of T cell lymphoma, c-MET is expressed in Karpas299 cells and some other ALCL cell lines." (PMID 27923392, 2016). "ALK-positive Anaplastic Large Cell Lymphoma (ALCL) represents a subset of Non-Hodgkin Lymphoma whose treatment benefited from crizotinib development, a dual ALK/MET inhibitor." (PMID 27662658, 2016).
anaplastic thyroid cancer (7 papers, 2016 to 2024). "In this study, it was shown that the anaplastic thyroid cancer (ATC)-derived TTA1 cell line overexpressed MET." (PMID 31040922, 2019).
Ewing sarcoma (7 papers, 2014 to 2024). A small round cell tumor that lacks morphologic, immunohistochemical, and electron microscopic evidence of neuroectodermal differentiation. "In contrast to the RON transcript, MET expression of Ewing sarcomas and cell lines remained below the MSC levels." (PMID 32272784, 2020). "They concluded that combining novel CAR-T cell therapy with the HGF receptor-neutralizing antibody Rilotumumab (AMG102) could enhance therapeutic efficacy, not only in Ewing sarcoma (EWS) but also in tumors with an abnormal activation of the HGF/c-MET pathway." (PMID 39204153, 2024). "MET gene expression was significantly upregulated by HOTAIR repression in ES2 and SK-ES Ewing Sarcoma cell lines and its expression was significantly repressed by HOTAIR over-expression in hTERT-immortalized human mesenchymal stem cells." (PMID 32650779, 2020).
fibrosarcoma (7 papers, 2007 to 2024). A malignant mesenchymal fibroblastic neoplasm affecting the soft tissue and bone. "In Lewis lung carcinoma and fibrosarcoma transplantation mouse models, tumor cell-derived TNFα prompts neutrophils to express the hepatocyte growth factor receptor (HGFR; also known as MET)." (PMID 36514901, 2022). "ADAMTS1 decreases fibrosarcoma cell proliferation and migration velocity by disrupting HGF/c-MET signaling." (PMID 35625488, 2022).
Hepatic steatosis (7 papers, 2016 to 2024). Steatosis is a term used to denote lipid accumulation within hepatocytes. "In diseases with exacerbated cell death, such as hepatic steatosis, one might restore the balance by favoring MET pro-survival signaling with ectopic HGF/SF treatment." (PMID 32091387, 2020).
Hypoalbuminemia (7 papers, 2015 to 2025). The concentration of albumin in the blood circulation is below the lower limit of normal. "Another cause of MET inhibitor‐induced edema is hypoalbuminemia." (PMID 39671301, 2025). "The only possibly related AE reported in more than 1 patient for LY2875358 monotherapy was hypoalbuminemia, which has previously been reported as a class-related effect for agents targeting MET/HGF." (PMID 27422720, 2016). "Edema, hypoalbuminemia and pulmonary embolism have been reported at rates higher than control in studies with other antibodies targeting MET or HGF." (PMID 26445503, 2015). "Given the key role that the HGF/MET axis plays in liver development and the role of the liver in albumin synthesis, hypoalbuminemia makes mechanistic sense as an expected event." (PMID 26445503, 2015). "Treatment-emergent hypoalbuminemia was also observed in other MET inhibitors." (PMID 35771259, 2022). "Therefore, it is plausible that SGLT2 inhibitors could also alleviate edema related to hypoalbuminemia induced by MET inhibitors." (PMID 39671301, 2025).
Insulin resistance (7 papers, 2015 to 2025). Increased resistance towards insulin, that is, diminished effectiveness of insulin in reducing blood glucose levels. "Growing evidence points to a special interest of the HGF/MET axis in the crosstalk with insulin resistance and obesity-related molecular signatures." (PMID 35269415, 2022).
malignant pleural mesothelioma (7 papers, 2012 to 2024). A malignant neoplasm that arises from mesothelial cells in the pleura and shows a diffuse growth pattern. "In malignant pleural mesothelioma, the combination of afatinib and MET/ALK/RON/ROS inhibitor crizotinib has been investigated in cell culture and mouse xenograft models." (PMID 31557260, 2019). "Combining MET and PI3K inhibition is efficacious in malignant pleural mesothelioma." (PMID 39458991, 2024).
retinoblastoma (7 papers, 2020 to 2023). A malignant tumor that originates in the nuclear layer of the retina. "We also used structural and functional prediction of the mutant RB and MET proteins to find interactions between the defected proteins with potential causative role in the development of this unique form of retinoblastoma." (PMID 33375764, 2020). "For example, the lncRNA HOTAIR/miR-613/c-MET signaling axis is involved in modulating the expression of EMT-specific proteins, apoptosis, and retinoblastoma cells’ viability." (PMID 35453574, 2022).
soft tissue sarcoma (7 papers, 2014 to 2024). A malignant neoplasm arising from muscle tissue, adipose tissue, blood vessels, fibrous tissue, or other supportive tissues excluding the bones. "In this study we aimed at investigating the HGF/MET axis in a comprehensive and well characterized cohort of various adult-type soft tissue sarcomas and GIST." (PMID 25844809, 2015). "Our results were obtained by up-to-date biomarker assays and provide first comprehensive epidemiologic data for ongoing and upcoming clinical trials with MET/HGF inhibitors in soft tissue sarcomas and GIST." (PMID 25844809, 2015). "Alveolar soft part sarcoma (ASPS) is a rare subtype of soft tissue sarcoma characterized by an unbalanced translocation, resulting in ASPSCR1-TFE3 fusion that transcriptionally upregulates MET expression." (PMID 35628499, 2022). "Compared with normal tissues and non-RMS pediatric soft-tissue sarcomas, only MEF2C showed significant and consistent up-regulation in RMS samples (also shown are MYOD and MET, genes that associate with RMS), data that point toward MEF2C as influential in RMS." (PMID 25491943, 2014). "Our screen revealed promising combinations with EGFRis, such as the ALK/MET-inhibitor crizotinib, the HDAC-inhibitor panobinostat or the topoisomerase-II-inhibitor doxorubicin, which are part of standard chemotherapy regimens for various bone and soft-tissue sarcomas." (PMID 34550531, 2021). "If not further specified “soft tissue sarcomas” are included in clinical trials with MET inhibitors it is conceivable that a considerable number of those patients would suffer from one of the liposarcoma entities which, based on our study, are unlikely to receive benefit from MET-targeted therapy." (PMID 25844809, 2015). "However, a systematic and comprehensive prevalence study of MET and HGF alterations in soft tissue sarcomas has not yet been published." (PMID 25844809, 2015).
/T cell lymphoma (6 papers, 2009 to 2024). "Peptide-induced helper T lines were observed to recognize and kill c-MET directly expressing NK/T-cell lymphomas and various epithelial solid tumors." (PMID 39664377, 2024). "Additionally, another study focused on the expression and function of c-MET in NK/T-cell lymphoma cells." (PMID 39664377, 2024). "In addition, HGF/c-MET were also expressed in natural killer/T cell lymphoma (NKTCL) cell lines." (PMID 27923392, 2016). "The expression of c-MET and its ligand HGF in NK/T-cell lymphoma cell lines, nasal NK/T-cell lymphoma specimens, and patient serum samples was confirmed." (PMID 39664377, 2024). "c-MET and HGF are expressed in natural killer/ T cell lymphoma cell lines and in nasal NK/T cell lymphoma specimens thus suggesting that also NK/T cell lymphoma proliferation may be induced through an autocrine loop." (PMID 30642077, 2019). "Additionally, MET expression is able to activate CD4+ T cells and can induce tumor cell killing in natural killer/T-cell lymphoma cell lines, in which MET elicits an anti-tumor immune response by increasing the activation of T cells and reducing the synthesis of TGF-beta." (PMID 33437521, 2020).
Alzheimer disease (6 papers, 2015 to 2026). A progressive, neurodegenerative disease characterized by loss of function and death of nerve cells in several areas of the brain leading to loss of cognitive function such as memory and language. "Together, the results of these studies support the potential of positive modulators of HGF/MET to be used as novel therapeutics and suggest the drug candidate fosgonimeton might protect against neurodegeneration and be therapeutic in the management of Alzheimer’s disease and other types of dementia." (PMID 36538176, 2023).
B cell lymphoma (6 papers, 2012 to 2024). "Currently, only two germ line missense mutations of c-MET have been found within B cell lymphoma, especially DLBCL (R1166Q in the tyrosine kinase domain in one patient and R988C in the juxtamembrane domain in four patients)." (PMID 27923392, 2016). "HGF increased the adhesion of c-MET-positive B cell lymphoma cells to fibronectin and collagen, mediated via β1-integrin, and furthermore, promoted migration and invasion." (PMID 27923392, 2016). "With the recent development of clinical-grade agents targeting the HGF/MET pathway, inhibition of this pathway is currently considered a rational and promising strategy for the treatment of patients with B-cell lymphoma and MM." (PMID 23379953, 2013). "The HGF/MET pathway is an emerging target for the treatment of MM, B-cell lymphomas and solid tumors." (PMID 23232072, 2012). "However, no amplification of the MET gene was found in B cell lymphoma cell lines and patient samples." (PMID 27923392, 2016).
brain cancer (6 papers, 2015 to 2025). A primary or metastatic malignant neoplasm affecting the brain. "Since 2009, the FDA has approved a number of multi-kinase inhibitors that target angiogenic growth factor receptors (e.g., VEGFR, PDGFR, FGFR, RET, c-KIT, MET, AXL and others) for treatment of malignant diseases, including brain cancer." (PMID 40076810, 2025).
chronic myeloid leukemia (6 papers, 2010 to 2024). "It has previously been shown that overexpression of MET is correlated with global L1 hypomethylation in chronic myeloid leukemia (CML)." (PMID 20421991, 2010).
colorectal tumors (6 papers, 2005 to 2025). "For example, low levels of FHIT and increased levels of a target of MIR7515, c-MET, have been linked to increased risk of metastasis of colorectal tumors." (PMID 30738427, 2019). "In addition, MET has been shown to be amplified in primary colorectal tumours as well as in liver metastasis." (PMID 15785735, 2005). "Similarly, KRAS G12D mutations and MAPK1 (MEK) and MET amplification are published biomarkers for colorectal tumor sensitivity to both MEK and MET inhibitors." (PMID 24621249, 2014). "Nevertheless, it is evident that MET is overexpressed in colorectal tumours with or without the presence of active Wnt signalling, implying an important role for MET in the onset and progression of CRC." (PMID 15785735, 2005).